FGF2 (fibroblast growth factor 2)
Diseases named in the same sentence as FGF2 in open-access papers (continued):
Sharing a sentence is not in itself a finding about the gene and the disease.
intestinal polyp (1 paper, 2012). Discrete abnormal tissue masses that protrude into the lumen of the intestine. "The expressions of angiogenesis activators VEGF and FGF-2 in these intestinal polyps were then evaluated by western blotting analysis." (PMID 22432006, 2012). "Riccardin D strongly inhibited the expressions of VEGF and FGF-2 and reduced the newly formed microvessel density in intestinal polyps." (PMID 22432006, 2012). "In this progression, VEGF and FGF-2 are important downstream targets of β-catenin that lead to endothelial cell proliferation to form vessels that support intestinal polyp growth and expansion." (PMID 22432006, 2012).
intrahepatic cholangiocarcinoma (1 paper, 2025). A carcinoma that arises from the intrahepatic bile duct epithelium in any site of the intrahepatic biliary tree. "Positive results for fibroblast growth factor 2 and isocitrate dehydrogenase 1/2 mutations have been reported in 11–45% and 10–20% of intrahepatic cholangiocarcinoma." (PMID 40075720, 2025).
Large vessel vasculitis (1 paper, 2019). A type of vasculitis (inflammation of blood vessel walls) affecting large arteries such as the aorta and branches of the aorta. "Therefore, the diagnostic clinical utility of serum FGF-2 needs to be confirmed in a cohort of large vessel vasculitis including LV-GCA and elderly-onset TAK." (PMID 30679579, 2019).
leukoplakia (1 paper, 2015). A white patch or plaque on a mucous membrane that cannot be characterized clinically or pathologically as any other disease. "Relative gene expression of FGF-2 was 28.62 fold higher in OSCC, 21.75 fold in Leukoplakia and 6.79 fold higher in OSMF as compared to healthy controls." (PMID 26465941, 2015).
lipoma (1 paper, 2017). A benign, usually painless, well-circumscribed lipomatous tumor composed of adipose tissue. "Lipomas can liberate angiogenic factors such as fibroblast growth factor-2 and vascular endothelial growth factor, giving rise to angiogenesis within the lipoma." (PMID 29423285, 2017).
macrosomia (1 paper, 2010). "A perusal of our observations suggests that human GDM and macrosomia are associated with down-regulation of GH and up-regulation of several growth factors, principally IGF-I, EGF, FGF-2 and PDGF-B." (PMID 20144210, 2010).
marginal zone B-cell lymphoma (1 paper, 2020). "Activation of (pro) renin receptor and AT1R triggers the pathogenesis of conjunctival extranodal marginal zone B-cell lymphoma by producing fibroblast growth factor 2 and matrix metallopeptidases." (PMID 32969473, 2020).
mastitis (1 paper, 2025). Inflammation of breast tissue during lactation or postpartum due to an obstructed duct or infection. "Considering that FGF–2 can form stable complexes with multiple mint components, FGF–2 can be further studied as a potential target for mint in the treatment of mastitis in dairy cows." (PMID 40005889, 2025). "Utilizing the PPI network, the topological parameters of Betweenness unDir, Closeness unDir, and Degree unDir were employed to predict the core targets for mint in treating mastitis in dairy cows, which include TNF, IL–6, STAT–3, IL–1β, FGF–2, IFNG, and ESR–1." (PMID 40005889, 2025).
melasma (1 paper, 2025). "The proliferation of blood vessels leads to an influx of inflammatory cells and cytokines (e.g., VEGF, TGF‐β, and FGF‐2) into the skin lesions, further forming a positive feedback loop to promote vascular proliferation in melasma." (PMID 40916844, 2025).
motor neuron disease (1 paper, 2020). "In research on ALS, the most common neurodegenerative motor neuron disease occurring in adulthood, FGF-2 isoform-specific ko mice were used to further elucidate the neuroprotective effect of complete or hemizygous ko of FGF-2 seen in mutant SOD1G93A mice." (PMID 33396566, 2020).
muscular dystrophy (1 paper, 2025). Muscular dystrophy (MD) refers to a group of more than 30 genetic diseases characterized by progressive weakness and degeneration of the skeletal muscles that control movement. "In another study, short-term treatment of skeletal muscle with FGF2 resulted in some improvement in number of regenerated myofibers in the mdx mouse muscular dystrophy model, but the effect was largely due to enhanced replication of satellite cells in the treated muscles." (PMID 40894678, 2025).
Myalgic encephalomyelitis (1 paper, 2021). "Reduction of TRPM3 (MIM 608961) is described to be associated with chronic fatigue syndrome/Myalgic encephalomyelitis patients, and FGF2 (MIM 134920) has been proposed to play a role in intussusceptive angiogenesis during COVID-19." (PMID 34452458, 2021).
myofascial pain syndrome (1 paper, 2023). Muscular pain in numerous body regions that can be reproduced by pressure on trigger points, localized hardenings in skeletal muscle tissue. "In a rat model of myofascial pain syndrome, the protein expression levels of FGF2 and p-FGFR1 were increased and the mechanical pain threshold was decreased, suggesting a role for FGF2/FGFR1 in myofascial pain." (PMID 36845134, 2023).
myringitis (1 paper, 2021). "Although an experimental study showed that application of high dosage of FGF2 caused myringitis and hyperplasia of the EAC, which may be avoided through application of an appropriate dosage by clinic." (PMID 34306094, 2021).
myxoid liposarcoma (1 paper, 2015). A liposarcoma characterized by the presence of round non-lipogenic primitive mesenchymal cells and small signet ring lipoblasts within a myxoid stoma with a branching vascular pattern. "Several FGFs are described to promote neoangiogenesis, among them FGF2 but also FGF5 and FGF18, for which an overexpression in myxoid liposarcomas was detected in this study." (PMID 26036639, 2015).
ocular neoplasms (1 paper, 2022). "Given the role of FGF2 as a potent pro-angiogenic mediator, several studies have investigated its involvement in ocular tumor-associated angiogenesis." (PMID 35409195, 2022).
orofacial cleft (1 paper, 2019). A disorder of facial skeleton that is characterized by cleft lip and/or cleft palate that result in feeding, speech and hearing problems caused by failures during development. "For example, previous studies show that SNPs in the miRNA-binding sites of MSX1, FGF2, FGF5 and FGF9 are associated with the susceptibility of nonsyndromic orofacial clefts." (PMID 31122291, 2019).
otosclerosis (1 paper, 2018). Formation of spongy bone in the labyrinth capsule which can progress toward the stapes (stapedial fixation) or anteriorly toward the cochlea leading to conductive, sensorineural, or mixed hearing loss. "Here, we genotyped eight previously associated variants in the following six candidate genes: RELN, BMP2, FGF2, COL1A1, TGFB1, and PPP2R5B in a large UK case–control otosclerosis cohort (n = 748)." (PMID 29728750, 2018).
ovarian dysfunction (1 paper, 2022). The inability of the ovaries to function. "This is consistent with our previous study that FGF2 had a protective effect on ovarian dysfunction in C57BL/6 mice administered cisplatin 2 mg/kg for 7 consecutive days." (PMID 35784556, 2022).
papillary adenocarcinoma (1 paper, 2017). A morphologic variant of adenocarcinoma. "The expression of VEGFD and FGF2 mRNA was significantly downregulated in lepidic and papillary adenocarcinomas when compared to adjacent normal lung tissues." (PMID 29137669, 2017).
paraplegia (1 paper, 2012). Complete paralysis of the lower half of the body including both legs, often caused by damage to the spinal cord. "In the present study, dMSCs and SKPs were isolated simultaneously from the same back skin sample from patients with paraplegia when SKP proliferation medium (DMEM/F12 containing 40 ng/ml FGF2 and 20 ng/ml EGF) was used during the initial stage." (PMID 23226248, 2012).
parasitic infection (1 paper, 2023). "Production of all molecules except FGF-2 and FGF-7 was significantly reduced in the CSF of EAE mice with parasitic infection." (PMID 36836678, 2023). "Production of AREG, EGF, FGF-2, and IGFBP-3 was significantly higher in the intestinal mucosa of colitic mice with parasitic infection than in the intestine of mice without induced disease but infected with H. polygyrus." (PMID 36836678, 2023).
pelvic inflammatory disease (1 paper, 2011). Pelvic inflammatory disease (PID) is an acute or chronic inflammation in the pelvic cavity. "In the future, it will be interesting to determine whether FGF2 contributes to pelvic inflammatory disease and whether other human adapted chlamdyial species, such as C. pneumoniae, utilize FGF2 to enhance infection." (PMID 21998584, 2011).
peripheral nerve lesion (1 paper, 2015). "During the repair phase following peripheral nerve lesion, dedifferentiated Schwann cells secrete a variety of neurotrophic factors and cytokines including NGF, BDNF, NT-4/5, FGF-2, IGF-1, IL-6, and IL-1ß that support neuronal survival and regenerative growth of axons." (PMID 26635533, 2015).
Pfeiffer syndrome (1 paper, 2020). Pfeiffer syndrome (PS) is a common form of acrocephalosyndactyly, a group of inherited congenital malformation disorders, characterized by variable degrees of bicoronal craniosynostosis, variable hand and foot malformations and various other associated manifestations. "For example, a KD of 2.4 × 10−8 M has been reported for the FGF2/FGFR1 complex from a patient with Pfeiffer syndrome." (PMID 33019532, 2020).
pilomatricoma (1 paper, 2025). "In contrast, the FGF2 oncogenic variant is a germline mutation expressed in all the somatic cells of the individual and, consequently, is also expressed in the pilomatricoma cells." (PMID 40843798, 2025).
placental insufficiency (1 paper, 2016). Failure of the placenta to deliver an adequate supply of nutrients and oxygen to the fetus. "The fact that PAI-1 levels and angiogenesis in turn are associated with hypoxia in placental insufficiency, and not its molecular angiogenic regulators VEGF and FGF-2, indicates upregulation may be largely through HIF-1 mediated mechanisms." (PMID 26903689, 2016).
pleural mesothelioma (1 paper, 2025). A neoplasm that arises from the mesothelial cells of the pleura. "Additionally, fibroblast growth factor 2 (FGF2) and epidermal growth factor (EGF) can promote a fibroblast-like phenotype with invasive traits and reduced cell adhesion in pleural mesothelioma." (PMID 40506895, 2025).
pulmonary edema (1 paper, 2020). Accumulation of fluid in the lung tissues causing disturbance of the gas exchange that may lead to respiratory failure. "Moreover, upregulation of the PI3K-Akt signaling pathway promotes expression of IL2, FGF2, and VEGFA, which aggravates inflammation, induces epithelial cell apoptosis, and increases vascular permeability and pulmonary edema." (PMID 33746744, 2020). "Ginseng could reduce the pathologic damage, neutrophil aggregation, proinflammatory factors, and pulmonary edema in vivo and inhibit the PI3K-Akt signaling pathway and MAPK signaling pathway through downregulating expressions of STAT3, VEGFA, FGF2, PIK3CA, MAPK1, and IL2." (PMID 33746744, 2020).
rectal cancer (1 paper, 2021). A primary or metastatic malignant neoplasm that affects the rectum. "Significant down‐regulation of FGF2 was observed in the post ganetespib treatment of rectal cancer patients." (PMID 34613665, 2021). "According to literature validation, we detected some rectal cancer‐related mRNAs including PRKCB, NCAM1, ZEB1, PCDH7, Cav1 and FGF2 in the subnetwork." (PMID 34613665, 2021).
renal dysfunction (1 paper, 2017). "FGF2 treatment greatly alleviated I/R‐induced acute renal dysfunction and largely blunted I/R‐induced elevation in serum creatinine and blood urea nitrogen, and also the number of TUNEL‐positive tubular cells in the kidney." (PMID 28544332, 2017).
Right ventricular hypertrophy (1 paper, 2024). In this case the right ventricle is more muscular than normal, causing a characteristic boot-shaped (coeur-en-sabot) appearance as seen on anterior- posterior chest x-rays. "Similarly, FGF2 expression is reportedly upregulated in patients with pressure or volume overload, causing left or right ventricular hypertrophy, and increased FGF2 levels are closely associated with human atrial fibrosis." (PMID 38355415, 2024).
salivary gland tumors (1 paper, 2014). "Fibroblast growth factor 2 (FGF2) and fibroblast growth factor receptor 1 (FGFR1) concentrations in saliva are significantly elevated in patients with salivary gland tumors making it a potential biomarker in the early detection of salivary gland tumors." (PMID 24616813, 2014).
skin squamous cell carcinoma (1 paper, 2022). A carcinoma arising from the squamous cells of the epidermis. "Moreover, ETV1 is reported to be significantly upregulated by FGF2 treatment and downregulated by TGF-β1, thus generating distinct cancer-associated fibroblasts populations to promote skin squamous cell carcinoma development." (PMID 36109787, 2022).
somatotropinomas (1 paper, 2019). "NF-PitNETs secreted higher amounts of cytokines/chemokines than somatotropinomas, especially CCL2 (16x more), IL-8 (25x more) and CCL4 (27x more), except for FGF-2 which was found in higher concentrations in somatotropinoma supernatants." (PMID 31703742, 2019).
steatosis (1 paper, 2025). Increased lipid within the cytoplasm of cells. "The secretion of FGF2 is increased in HFD-induced obese mice while its global knockout mice are resistant to HFD-induced adiposity and steatosis by increasing UCP1-activated thermogenesis, which requires the involvement of heparin." (PMID 40180176, 2025).
Strabismus (1 paper, 2025). A misalignment of the eyes so that the visual axes deviate from bifoveal fixation. "In individuals with overacting muscles causing strabismus, sustained FGF2 treatment has the potential to improve alignment by weakening the appropriate muscle." (PMID 40894678, 2025).
synovial chondromatosis (1 paper, 2020). Synovial chondromatosis is a type of non-cancerous tumor that arises in the lining of a joint. "Moreover, relative studies had reported that fibroblast growth factor 2 (FGF-2) or transforming growth factor beta 3 (TGF-β3) were responsible for the formation of cartilaginous loose bodies and involved in the pathogenesis of synovial chondromatosis." (PMID 32534572, 2020).
systemic candidiasis (1 paper, 2019). "Systemic Candida infections pose a serious risk with high mortality rates; thus, a new approach to block host FGF-2 functions during systemic infections could be an effective treatment option." (PMID 30841504, 2019). "To evaluate the role of FGF-2/angiogenesis in systemic candidiasis, we infected mice with the wild-type strain SC5314 via a lateral tail vein either alone or in addition to two FGF-2 (1.6 μg) treatments (at 3 h and 5 h post-infection)." (PMID 30841504, 2019). "Finally, using a murine model of systemic candidiasis, we discovered that treatment of C. albicans infected animals with FGF-2 results in increased mortality, suggesting that C. albicans induces FGF-2/angiogenesis to enhance pathogenicity." (PMID 30841504, 2019).
tauopathy (1 paper, 2024). Neurodegenerative disorders involving deposition of abnormal tau protein isoforms (tau proteins) in neurons and glial cells in the brain. "To assess the impact of tau pathology on FGF2 expression, we analyzed FGF2 expression in human mutant tau (P301L)-overexpressing hippocampal neurons and tauopathy model mice." (PMID 38951140, 2024).
Tendon rupture (1 paper, 2024). Breakage (tear) of a tendon. "This study aims to investigate the efficacy of FGF-2 in promoting tendon healing in a rat model of Achilles tendon rupture, providing insights into its potential as a therapeutic option." (PMID 39483374, 2024).
testicular cancer (1 paper, 2013). A primary or metastatic malignant neoplasm that affects the testis. "Therefore, FGF-2 may represent a promising new diagnostic marker for testicular cancer with high sensitivity." (PMID 24159602, 2013). "FGF-2 was elevated in the tissue and serum of patients with testicular cancer, including the seminomatous as well as nonseminomatous tumors." (PMID 24159602, 2013).
thoracic cancer (1 paper, 2022). A primary or metastatic malignant neoplasm affecting the tissues of the thorax. "It has already been reported that Cisplatin increases cytokines and growth factors as IL6, IL8 and FGF2 in solid tumors, including thoracic cancers." (PMID 35880098, 2022).
thrombotic disorders (1 paper, 2012). "Here we demonstrate that sulodexide – a combination of GAGs composed of heparin-like (80%) and dermatan fractions (20%) that is currently used to treat thrombotic disorders and DN - is an effective HPSE inhibitor capable of preventing FGF-2-induced EMT in renal tubular cells." (PMID 23095131, 2012).
tonsillitis (1 paper, 2023). Inflammation of the tonsillar tissue. "Next, we sorted PI16+ RCs and TRCs as a control population from adult patients with OSA and tonsillitis and stimulated the in vitro cultured FRC subsets with TGF-β1, TGF-β3, LIGHT or FGF2." (PMID 37202490, 2023).
urothelial carcinomas of the urinary bladder (1 paper, 2023). "In the present study, we evaluated the expression of fibroblast growth factor-2 (FGF2) in early-stage urothelial carcinomas of the urinary bladder (pTa and pT1) regarding the invasive potential of these tumors." (PMID 36843751, 2023).
uterine tumors (1 paper, 2024). "Meanwhile, anti‐FGF2 monoclonal antibody (3F12E7) could decrease newborn lymphatic vessels in both intratumoral and peritumoral regions of orthotopic uterine tumors." (PMID 39119899, 2024).
uveitis (1 paper, 2020). An inflammatory process affecting a part of or the entire uvea. "Finally, some of those genes are known to be involved in retinal function but not during uveitis specifically, such as Clu, Lrg1 and Fgf2." (PMID 32183784, 2020).
ventricular dilatation (1 paper, 2021). "The study showed that intramyocardial injection of FGF2 (plus heparin) in rats with hypertensive myocardial hypertrophy was associated with significant improvements in systolic pumping function and ventricular dilatation, as well as an increase in myocardial capillary density." (PMID 34204341, 2021).
Vestibular schwannoma (1 paper, 2021). A vestibular schwannoma (also known as acoustic neuroma, acoustic neurinoma, or acoustic neurilemoma) is a benign, usually slow-growing tumor that develops from the VIIIth cranial nerve supplying the inner ear. "This potential therapeutic effect in hearing is in line with previous findings of elevated levels of vestibular schwannoma-secreted FGF2 being associated with better hearing." (PMID 35002617, 2021).
X-linked hypophosphatemia (1 paper, 2022). X-linked hypophosphatemia (XLH) is a hereditary renal phosphate-wasting disorder characterized by hypophosphatemia, rickets and/or osteomalacia, and diminished growth. "We have used Basic Fibroblast Growth Factor (FGF2) transgenic mice as experimental models for human X-linked hypophosphatemia (XLH)-related degenerative osteoarthritis (OA) to investigate the pathogenesis of the disease and to test potential pharmacotherapies for treatment." (PMID 36153352, 2022).